INS (insulin)
Diseases named in the same sentence as INS in open-access papers (continued):
Sharing a sentence is not in itself a finding about the gene and the disease.
Insulin resistance (continued). "Adiponectin is suggested to counteract insulin resistance by boosting lipid oxidation via activation of AMP-activated protein kinase (AMPK), and the cross-talk of adiponectin with insulin signaling thus is thought to improve glycogen synthesis and glucose transport." (PMID 36289764, 2022). "While the Matsuda index is considered a good indicator of insulin sensitivity, there is no agreed threshold value for detecting insulin resistance, although an upper threshold of four has been suggested." (PMID 35458200, 2022). "In this case, the increased blood glucose levels will continuously stimulate the secretion of insulin, but not sufficiently to reduce elevated blood glucose levels, depending on how far the insulin resistance has proceeded." (PMID 35216316, 2022). "Additionally, IL-1β depletion completely changes the inhibitory effect of MC medium on insulin signaling molecules like IRS-1 and PI3K, which indicates that IL-1β is a key factor in mediating macrophage-induced insulin resistance in adipocytes." (PMID 36230963, 2022). "Moreover, MAPK8 plays an essential role in the development of insulin resistance and obesity, whereas MAPK8 knockout mice displayed improved adiposity and insulin sensitivity." (PMID 36386135, 2022). "Women with a history of GDM are therefore more likely to develop insulin resistance in a nonpregnant state, and insulin sensitivity is further reduced." (PMID 35373529, 2022). "The majority of East Asian T2D patients, including Japanese, present insulin secretion defect rather than insulin resistance." (PMID 35351190, 2022). "show that hepatic insulin resistance did not impact the SREBP1c pathway and continued to produce TG by the insulin-resistant hepatocytes." (PMID 36479211, 2022). "In the present study, we report differential increase in expression of both PHLPP1 and PHLPP2, in hyperinsulinemia mediated insulin resistance in two neuronal cell lines in vitro, with or without insulin stimulation." (PMID 36376971, 2022). "Moreover, transgenic mice overexpressing human RBP4, and mice injected with recombinant RBP4 exhibit insulin resistance, while the genetic deletion of RBP4 enhances insulin sensitivity in mice." (PMID 35406450, 2022). "Moreover, AAV-shFGF9 treatment further aggravated glucose intolerance and insulin resistance induced by HFD, and impaired hepatic insulin signaling." (PMID 35517790, 2022). "The findings of this specific lesson indicated that individuals with the conventional PCOS phenotype had obesity and higher insulin levels and insulin resistance, neglecting the absence of BMI differences from other phenotypes." (PMID 36407241, 2022). "As a bridge between inflammation and insulin, inflammatory factors promote the phosphorylation of IRS-1 at the Ser307 site by activating JNK phosphorylation, thereby hindering insulin signaling and exacerbating insulin resistance." (PMID 35745162, 2022). "On the other hand, an animal study showed that 24 weeks of supplementation with leucine in rats fed a high-fat diet improved insulin sensitivity, and BCAA supplementation in persons with chronic liver disease with insulin resistance reportedly improved HOMA-IR." (PMID 36235570, 2022). "Insulin resistance refers to a pathological state in which the body’s intake and utilization of glucose is reduced by a lack of a response to insulin." (PMID 35330934, 2022). "Importantly, we observed a reduction in insulin resistance, demonstrating the role of TRF in enhancing the effects of insulin." (PMID 36362316, 2022). "It has been argued that low insulin clearance is a primary determinant of peripheral insulin levels rather than a compensatory mechanism for insulin resistance." (PMID 34661756, 2022). "HOMA-IR, an indicator of insulin resistance, was found to increase in both mouse groups under HFD conditions, but significantly decrease in Redd1−/− mice, suggesting an improvement in insulin sensitivity and resistance in Redd1−/− mice." (PMID 36272977, 2022).
Insulin resistance (continued). "Impaired insulin signaling in the lungs of Mtb infected adult mice: Our data demonstrated that Mtb infected adult mice developed hyperglycemia and insulin resistance (based on the HOMA IR levels) irrespective of diet." (PMID 35329973, 2022). "In particular, the adipokines resistin, leptin, PAI-1 and retinol binding protein 4 (RBP4) induce insulin resistance in megakaryocytes by interfering with IRS-1 expression with a negative impact on insulin signalling in platelets." (PMID 35250588, 2022). "The M1 polarization mediated by miR-29 through TRAF3, triggered not only islet infiltration but also macrophage migration to insulin-target tissues (liver, skeletal muscle and white adipose tissue; WAT), resulting in systemic inflammation and insulin resistance." (PMID 36619588, 2022). "A low T is correlated with lower insulin sensitivity in men; insulin resistance does not affect T but the reverse is true, since T lowers insulin resistance, and helps maintain glycaemia." (PMID 36233256, 2022). "Together, these findings highlight the important role GATA3 plays in the development of impaired adipogenesis and insulin resistance, therefore blocking GATA3 could reverse these mechanisms and enhance both adipogenesis and insulin signaling." (PMID 36232443, 2022). "Changes in waist circumference or fatty liver index correlated with changes in glycemia and insulin resistance, but not with changes in insulin secretion." (PMID 36432409, 2022). "Given the rise in abdominal obesity in parallel to insulin resistance and NAFLD, attention has been given to the significant role that a lipolysis-driven rise in plasma NEFA plays in linking hepatic insulin resistance to reduced insulin clearance." (PMID 36009446, 2022). "Since the fat body is a major target for insulin signaling, we wondered whether increased insulin signaling in HSD led to insulin resistance." (PMID 36201241, 2022). "Blood pressure, fasting glucose and insulin, and insulin resistance decreased (p < 0.05) from baseline regardless of treatment without any change in body mass." (PMID 35458108, 2022). "Since TNF-α could induce insulin resistance, the effect of fermented SS on glucose uptake was investigated in TNF-α-induced FL83B cells in the presence of insulin." (PMID 35893262, 2022). "Disorders of the insulin-signalling pathway are emerging as common hallmarks of both AD and DM; nevertheless, the emphasis thus far has been on T2DM, with hyperinsulinemia and insulin resistance serving as the key insults." (PMID 35802659, 2022). "Due to lack of insulin or insulin resistance, the extracellular glucose concentration increases significantly." (PMID 35656112, 2022). "Accordingly, a separate study revealed that dietary intake of bacterial indole-3-priopionic acid reduces fasting glucose, fasting insulin, and the HOMA insulin resistance index in rats, substantiating the clinical findings of the positive association between IPA and insulin sensitivity." (PMID 36144238, 2022). "Although SC-fed IL-6Ra KD mice exhibit elevated plasma IL-6 levels, they do not display insulin resistance, as denoted by the insulin tolerance tests." (PMID 35470093, 2022). "For women with an uncomplicated index pregnancy, those who were obese had significantly higher serum insulin, insulin resistance, and CRP levels than women who were not obese in early pregnancy." (PMID 35817936, 2022). "Another meta-analysis of several clinical studies revealed that probiotics may effectively lower fasting insulin, hemoglobin A1c, and FBG while enhancing the effectiveness of homeostatic model assessment of insulin resistance." (PMID 36144408, 2022). "However, insulin sensitivity is inversely related to the RMR, which indicates that with consumption of UPFs, hs-CRP levels, inflammation, and insulin resistance increase, which has a decreasing effect on the RMR." (PMID 36313082, 2022).
Insulin resistance (continued). "Furthermore, the use of metformin, insulin sensitizers, and IIA affected the assessment of insulin resistance, and HOMA2-IR was corrected to assess the correlation between UAE, eGFR, and atherosclerosis." (PMID 35413936, 2022). "Plasma glucose and insulin levels were reduced after resveratrol supplementation as compared to the non-supplemented group, meaning that insulin resistance was reduced." (PMID 36687699, 2022). "We also studied subgroups to evaluate the effects of obesity independent of insulin resistance, and insulin resistance independent of obesity on insulin kinetics." (PMID 34905513, 2022). "In addition, chemerin levels correlated positively with gestational BMI, Homeostatic Model Assessment-Insulin Resistance (HOMA-IR), and glucose, and leptin levels with HOMA-IR, and insulin." (PMID 35682958, 2022). "Although the main cause of T1DM is the absolute lack of insulin secretion, most patients have insulin resistance at the same time, and this feature runs through the beginning of the disease and the subsequent insulin treatment process." (PMID 36530444, 2022). "As insulin has an inhibitory effect on GDF15 secretion, hepatic insulin resistance may augment secretion of GDF15." (PMID 36545337, 2022). "The obesity-induced increase in insulin secretion, in conjunction with a decrease in insulin clearance, sufficiently raised the plasma insulin concentrations needed to maintain normoglycemia in individuals with moderate, but not severe, insulin resistance." (PMID 34905513, 2022). "It is also important to consider why an association was observed in early adolescence but not earlier in childhood and only with adiponectin and insulin, but not with other markers of insulin resistance such as glucose or HOMA-IR." (PMID 33824455, 2022). "Overnutrition augments mTORC1 signaling, which in turn may generate insulin resistance via mTORC1/S6K-mediated IRS1 serine phosphorylation as well as the degradation of its total protein levels, attenuating the insulin signaling pathway." (PMID 35428325, 2022). "Impaired glucose homeostasis was apparently not accompanied by peripheral insulin resistance since levels of liver pAkt, a downstream target of the insulin signaling pathway, remained similar between WT and tau KI animals." (PMID 35250480, 2022). "As expected, the correlation between insulin and HOMA1-IR index was strong (r = 0.99 at baseline, P < 0.001), while there was a negative correlation between insulin resistance and insulin sensitivity (r = −0.90, P < 0.001)." (PMID 36137169, 2022). "While the current article is focused on serum sphingolipids and insulin resistance, they are certainly not the only circulating lipid signals that can impact insulin sensitivity." (PMID 36030929, 2022). "Similar to Waved 2 mice, global AREG−/− mice were protected against insulin resistance in response to the HFD, as indicated by lower body weight and fasting blood glucose as well as improved glucose tolerance tests and insulin tolerance tests compared to WT mice." (PMID 35948530, 2022). "They propose a relationship between hypertension and insulin resistance and not with insulin production." (PMID 35631313, 2022). "Recent data place hyperinsulinemia mechanistically upstream of insulin resistance and suggest that insulin hypersecretion, rather than beta cell dysfunction, identifies otherwise normal individuals at risk for type 2 diabetes." (PMID 35897752, 2022). "Excessive chronic IL-6 production promotes the development of insulin resistance and T2D by impairing the phosphorylation of IR and IRS-1 via the upregulation of SOCS-3 (suppressor of cytokine signaling 3), a potential inhibitor of insulin signaling." (PMID 35629988, 2022). "Reduction of IHL during the intervention by 42% significantly improved insulin sensitivity [homeostatic model assessment for insulin resistance (HOMA-IR) or hyperinsulinemic euglycemic clamps] but not fasting GCGN or AA levels." (PMID 35662921, 2022).
Insulin resistance (continued). "Moreover, EBRT significantly decreased serum levels of insulin (p = 0.035), TNF-α (p = 0.046), hsCRP (p = 0.037), and insulin resistance (p = 0.045) as well as body fat percentage (p = 0.023)." (PMID 36207735, 2022). "A small-scale study on individuals with insulin resistance found that IP6K1 levels (protein and mRNA) deceased under conditions of high intensity exercise that correlated with improved insulin signaling, supporting an antagonistic role for insulin signaling by IP6K1 in humans." (PMID 35743190, 2022). "In addition, calculations of HOMA-IR, insulin DI, and QUICKI index were conducted to evaluate insulin resistance." (PMID 35655590, 2022). "Increasing evidence strongly points to disordered insulin secretion rather than insulin resistance playing a central role in driving the development of T2DM." (PMID 36482911, 2022). "Abdominal fat does not respond well to the antilipolytic action of insulin, leading to insulin resistance and therefore T2D." (PMID 36297122, 2022). "Impaired signaling results in insulin resistance—a condition that preludes type 2 diabetes (T2D)—in which normal amounts of insulin are inadequate to stimulate insulin response from fat, muscle, and liver cells." (PMID 35678366, 2022). "Intraperitoneal-insulin-administration-induced Akt phosphorylation was impaired in HFD hearts, which was restored by ANP treatment, suggesting that ANP treatment ameliorated myocardial insulin resistance." (PMID 35955507, 2022). "Among males, who were more insulin resistant to begin with (no genotype differences before treatment), tended to be more sensitive to CL-mediated reduction in insulin resistance." (PMID 36213237, 2022). "Finally, taken together, these data show that DPP4 may negatively affect insulin sensitivity and secretion, favoring mechanisms leading from chronic caloric excess and positive energy balance to body weight gain and development of insulin-resistance-related diseases." (PMID 36140405, 2022). "In states of insulin resistance, IR-dependent molecular cascades may start to be insensitive to this hormone, leading to brain insulin resistance (BIR), and in this situation, insulin lose its ability to improve plasticity." (PMID 35406040, 2022). "Insulin resistance and hyperglycemia as features of T2DM have a detrimental effect on cognitive abilities, since insulin and insulin-like growth factor, also called somatomedin C (IGF-1), play an important role in cognitive ability, neural function, and development." (PMID 35563031, 2022). "In addition to a reduction in total cholesterol, there was a 0.75 μIU/mL decrease in fasting insulin (p = 0.045), and the HOMA-IR insulin resistance index fell by 0.21 compared with the start of the study (p = 0.01)." (PMID 35406013, 2022). "↓FBG, serum insulin, CRP, and MDA; ↑TAC and GSH; and improved insulin resistance scores." (PMID 35052633, 2022). "Interestingly, the plasma insulin and HOMA-IR index, a measure of insulin resistance, were significantly higher in HF+MA-fed mice compared to HF controls." (PMID 35740864, 2022). "In females, positive correlations were identified between serum L-C and obesity, total cholesterol, glucose, insulin, and insulin resistance in those with normal fasting glucose level, but not if hyperglycemic." (PMID 35366920, 2022). "Hyperleptinemia in the absence of high fat diet and/or obesity improves insulin sensitivity and glucose uptake and only elicits leptin- and insulin-resistance in the context of diet-induced obesity." (PMID 35721743, 2022). "As expected, our study found that B. laterosporus BL1 treatment significantly improved glucose tolerance and insulin resistance in HFD-induced mice, as evidenced by markedly reduced fasting blood glucose and fasting serum insulin as well as improved IGTT and ITT." (PMID 36505236, 2022). "PDA does not directly stimulate insulin overexpression at pancreatic islet beta cells but synthesizes products to elicit insulin resistance in the human body." (PMID 35252207, 2022).
Insulin resistance (continued). "Compared with non-Asians, Asian individuals are more insulin resistant and have lower beta cell function to overcome insulin resistance." (PMID 35331213, 2022). "The secretion of pancreatic β cells fails to meet the demand for insulin required by hyperglycemia and insulin resistance." (PMID 36295827, 2022). "The lack of any association of TSH with metabolic parameters of insulin resistance can be estimated as another similarity to our study, where TSH was only associated with 2-h postload insulin with regard to continuous variables." (PMID 35085102, 2022). "Similarly, genistein treatment decreased insulin markers in rats with PCOS such as insulin and glucose, as well as insulin resistance." (PMID 34995042, 2022). "When insulin resistance reaches the extent that the β-cell no longer compensates, insulin secretion decreases, and hyperglycemia develops." (PMID 35893594, 2022). "In general, males suffer more often from impaired fasting glucose levels driven by increased hepatic glucose output and dysfunctional early insulin secretion, whereas in females a higher occurrence of impaired glucose tolerance (IGT), mediated via peripheral insulin resistance, has been observed." (PMID 34223999, 2022). "In diabetic patients, either the pancreas are unable to produce enough insulin hormone or the cells in the body are not responding to insulin (insulin resistance)." (PMID 35808352, 2022). "Not only increased PGRN levels in blood correlated positively with body mass index (BMI), fat mass, fasting glucose and insulin levels, and insulin resistance, but also mediated TNF-a-induced insulin resistance through the regulation of IL-6 expression in 3T3-L1 adipocytes." (PMID 35419363, 2022). "Insulin resistance is a negative physiological state in which the body or cells are not sensitive to insulin, and it is difficult for insulin to be functional." (PMID 36558381, 2022). "This hypothesis fits well with the finding that vitamin B6 supplementation is able to enhance insulin sensitivity, by increasing AKT phosphorylation and the expression of AKT downstream genes, in insulin‐resistant mice." (PMID 35678366, 2022). "Akin to the skeletal muscle that accounts for 70%-80% of insulin-stimulated glucose disposal, inhibition of the IRS-1 ubiquitin pathway may also engage in alleviating insulin resistance." (PMID 36045953, 2022). "While initially reported to be a response against obesity-related insulin resistance, research has indicated that increased insulin secretion can develop in the absence of insulin resistance implying primary beta-cell pathology." (PMID 35984746, 2022). "This meta-analysis demonstrated that selenium supplementation may reduce the levels of serum insulin and HOMA-IR, and increase serum HDL-C levels, suggesting that selenium supplementation may be beneficial for reducing insulin resistance in patients with CMDs." (PMID 36432623, 2022). "Although most of the observed hyperinsulinemia in PCOS is probably secondary to insulin resistance, there seems to be an important component of abnormal insulin secretion, which is independent of insulin resistance, body weight, and body fat distribution." (PMID 35646110, 2022). "Decreased insulin or dysregulation of insulin signaling could be therapeutic targets in DPN in T1D, because insulin resistance is characteristic in the SN and DRG in both T1D and T2D." (PMID 36477360, 2022). "Herein, insulin was not measured, but the assessment of insulin resistance via conventional methods can help better understand the function of this drug and its effects on metabolism." (PMID 34904397, 2022). "They obtained that although there is lipid accumulation in skeletal muscles, insulin resistance in lean PCOS women with hyperandrogenism is not a consequence of injuries in the proximal part of the insulin-signaling cascade in skeletal muscles." (PMID 35052811, 2022).